LINC01433 (long independently transcribed non-coding RNA 1433)
Synonyms: LOC728228
Gene: Long non-coding RNA gene on chromosome 20 (4,192,932 to 4,195,953, forward strand). Ensembl gene ENSG00000230176.
Diseases named in the same sentence as LINC01433 in open-access papers:
LINC01433 is named in the same sentence as 2 diseases in open-access papers, as found by Europe PMC text mining. Sharing a sentence is not in itself a finding about the gene and the disease. The quoted sentences say what the papers report.
infection (1 paper, 2021). The state of being infected such as from the introduction of a foreign agent such as serum, vaccine, antigenic substance or organism. "As HIF1A-AS1 and LINC01433 did not change the tendency at three time points of Ct infection (HIF1A-AS1 expression was upregulated at all three time points, while LINC01433 was downregulated), FGD5-AS1 and LINC00707 were chosen for further study." (PMID 34568091, 2021).
LINC01433 also shares sentences with these, for which no sentence is quoted: cancer (1 paper).